INS (insulin)
Diseases named in the same sentence as INS in open-access papers (continued):
Sharing a sentence is not in itself a finding about the gene and the disease.
Insulin resistance (continued). "Insulin resistance (IR), an independent risk factor for the development of type 2 diabetes mellitus (T2DM) and other metabolic syndromes, is a pathological state characterized by failure of the insulin system." (PMID 38745311, 2024). "Insulin resistance denotes an impaired response of target tissues when exposed to insulin." (PMID 38248762, 2024). "Therefore, we conducted an IPITT, assessed fasting insulin levels, and calculated the homeostasis model assessment of insulin resistance (HOMA-IR)." (PMID 39156823, 2024). "According to existing reports, BMI was significantly correlated with insulin resistance, increased BMI occurred earlier than insulin resistance, and BMI interventions could significantly improve insulin sensitivity." (PMID 38764021, 2024). "Mechanistically, fat overload in the liver may lead to the accumulation of diacylglycerol, which activates protein kinase Cε (PKCε), impairing insulin signaling and leading to insulin resistance." (PMID 39458518, 2024). "The serum insulin levels in the MC group exhibited a significant increase, and the homeostasis model assessment of insulin resistance (HOMA-IR) of the MC group was 4.82 times elevated compared to the NC group, suggesting that the mice exhibited severe insulin resistance." (PMID 39765819, 2024). "This may be due to the severely elevated fasting insulin levels reflecting the overall increased insulin resistance in the subgroup." (PMID 38276866, 2024). "However, db/db Arg2 had significantly lower glucose tolerance testing (GTT) areas under the curve (AUC), fasting insulin, and lower homeostatic model assessment for insulin resistance (HOMA-IR) vs db/db controls." (PMID 38280549, 2024). "Pro-inflammatory cytokines could play roles in insulin resistance through different mechanisms such as inducing inflammatory pathways or insulin signaling pathway modification." (PMID 38409315, 2024). "GLP-1R agonists, by regulating insulin release and lowering blood glucose levels, may help improve insulin resistance and glucose metabolism disorders, indirectly protecting the nervous system from damage." (PMID 39719978, 2024). "Our study revealed that, after insulin induction, the model group’s glucose consumption was significantly decreased, confirming insulin resistance, with an average of 421.56 ± 6.45%, compared to the blank group that had a notably higher consumption at 960.64 ± 26.67% (p < 0.05)." (PMID 38472847, 2024). "Insufficient β-cell compensation for maternal insulin resistance contributes to reduced insulin secretion and impaired glucose tolerance, characteristic of GDM7.GDM may have an adverse effect on the health of mothers and offspring." (PMID 38802412, 2024). "They found that excessive insulin secretion in adolescents was associated with the development of obesity and glucose intolerance in later life, independent of insulin resistance." (PMID 39769002, 2024). "Dysfunctional adipose tissue releases molecules such as free fatty acids (FFAs), reactive oxygen species (ROS), and pro-inflammatory cytokines (leptin, IL-6, TNF-Alpha, etc.), leading to impairment in insulin-signaling pathways and subsequent insulin resistance." (PMID 39337412, 2024). "We found associations between increased insulin or insulin resistance and impaired measures of clinical outcome, such as nonremission, poor daily functioning and transition to psychosis, in CHR." (PMID 39085221, 2024). "In a study that aimed to demonstrate that metformin therapy improves insulin sensitivity and vascular health in adolescents with T1DM, metformin was demonstrated to ameliorate insulin resistance despite baseline BMI, weight, fat mass, insulin dosage, and aortic and carotid health." (PMID 39768947, 2024). "Furthermore, inflammatory conditions impair vascular reactivity and insulin delivery, fostering insulin resistance." (PMID 39224122, 2024).
Insulin resistance (continued). "Elevated urea nitrogen levels in vivo may induce insulin resistance, inhibit insulin secretion, reduce glycolytic flux, and attenuate insulin signaling." (PMID 38379868, 2024). "Insulin resistance (IR), a pathological state in which the body's tissues become resistant to the effects of insulin, leading to hyperinsulinemia and compensatory hyperglycemia, is a common feature of PCOS, with up to 70% of women with PCOS exhibiting some degree of IR." (PMID 39276209, 2024). "Under the induction of saturated fatty acids, miR-183-5p might impair insulin signaling, potentially contributing to the development of insulin resistance." (PMID 39595174, 2024). "Insulin resistance, also known as impaired insulin sensitivity, is due to the decreased reaction of insulin signaling for glucose levels, seen when glucose use in response to an adequate concentration of insulin is impaired." (PMID 38397072, 2024). "Leptin may have a role in the development of hepatic steatosis by promoting insulin resistance and altering insulin signaling in liver cells, leading to an increased accumulation of fatty acids inside the cells." (PMID 39229578, 2024). "Furthermore, in T2DM mice models (C57BL/KsJ-db/db) and the high-fat diet-induced insulin resistance model, quercetin was observed to reduce the skeletal glucose uptake with subsequently influencing the insulin secretion (glucose-stimulated)." (PMID 38255714, 2024). "Recent studies have indicated that the etiology of type II (non-insulin-dependent) diabetes mellitus involves various factors, including impaired insulin secretion, reduced insulin activity, environmental factors, and genetic factors related to insulin resistance." (PMID 38398628, 2024). "Lastly, it may well be that the marked decrease in insulin levels and/or in insulin resistance has a role in accelerating the decrease in liver steatosis." (PMID 38542785, 2024). "Furthermore, it has been reported that homocysteine induces insulin resistance in vitro by inhibiting insulin signaling, with this effect being mediated by oxidative stress." (PMID 39468643, 2024). "Since Srebp1 is regulated by insulin, the observed changes in its expression suggest that both LDI and HDI could improve insulin resistance caused by a high-fat diet." (PMID 39268531, 2024). "However, prolonged insulin resistance and increased demand for insulin can lead to pancreatic beta-cell dysfunction and reduced insulin production." (PMID 38542928, 2024). "Notably, improvements induced by HB in insulin sensitivity, fasting blood glucose levels, leptin, and adiponectin effectively prevented insulin resistance, reduced weight gain, and improved glycolipid metabolism and antioxidant capacity in rats with obesity." (PMID 39458511, 2024). "The study population consisted of children with obesity and insulin resistance, stratified according to the post-challenge insulin peak timing (i.e., early, middle, and late peak), from whom fasting and postprandial plasma and erythrocytes were collected for metabolomics analysis." (PMID 39192263, 2024). "Mice with elevated GPx-1 expression exhibit a T2D-like phenotype characterized by obesity, hyperglycemia, hyperlipidemia, hyperinsulinemia, insulin resistance, increased pancreatic β-cell mass, glucose-stimulated insulin secretion, elevated plasma leptin levels, and hepatic lipogenesis." (PMID 39469571, 2024). "Homeostatic model assessment (HOMA) which is the product of fasting plasma glucose and fasting plasma insulin is a valuable indicator that has been used extensively in epidemiological studies of various ethnic origins to assess β-cell function and insulin resistance." (PMID 38977979, 2024). "The potential implication is that higher zinc levels may destabilize insulin hexamers and hinder their storage in the pancreas, particularly in women with insulin resistance." (PMID 38694665, 2024).
Insulin resistance (continued). "According to earlier research, women who are normoglycemic but will develop GDM have a pre-existing degree of insulin resistance as a result of minor abnormalities like excessively high levels of immature insulin synthesis or unusual pulsatile insulin patterns." (PMID 39355538, 2024). "Insulin resistance refers to the body’s compensatory secretions of more insulin to maintain blood glucose, leading to decreased efficiency of glucose uptake and utilizing insulin, eventually resulting in hyperinsulinemia to maintain stable blood glucose levels." (PMID 39114293, 2024). "Another possible effect of FST overexpression on muscle is by improving insulin resistance which reinforces insulin’s action and increases insulin-stimulated intracellular insulin signaling of AKT/mTOR that increases protein synthesis and up-regulates muscle mass." (PMID 38409184, 2024). "The blood glucose level, insulin level, and insulin resistance (IR) were detected." (PMID 39220593, 2024). "We suggest that the glucose uptake-associated phosphosites we have identified will be enriched in major regulators of insulin responsiveness, necessitating future functional studies to characterise these sites and explore their involvement in insulin resistance." (PMID 38329473, 2024). "We will emphasize that it serves as a surrogate marker, which can provide insights into insulin sensitivity, but it may have limitations when compared to more direct and precise methods for measuring insulin resistance." (PMID 38218819, 2024). "PI3K inhibition leads to insulin resistance, interrupting glucose uptake in muscle and adipose tissue, thereby activating hepatic glycogenolysis, resulting in hyperglycemia and compensatory increase in insulin." (PMID 38584192, 2024). "Subsequently, the improvement in insulin sensitivity may therefore reduce inflammation and the release of cytokines that promote insulin resistance." (PMID 38540173, 2024). "Unmeasured fetal or placental factors that can influence insulin resistance might affect antenatal insulin treatment outcomes." (PMID 39346677, 2024). "However, fructose contributes to hepatic insulin resistance through increased accumulation of hepatic diacylglycerol, activation of protein kinase C, impairment of insulin-mediated Akt2 activation, and blocking of hepatic β-fatty acid oxidation." (PMID 39458565, 2024). "Importantly, the induction of inflammation together with systemic insulin resistance and impaired insulin signaling in the liver was most evident when both postnatal overfeeding and hyperandrogenemia were present." (PMID 39268230, 2024). "Similarly, studies investigating selenium intake, with an RDA of 55 μg/day, highlight improvements in glucose levels, insulin sensitivity, reduction of insulin resistance, decreased blood lipids, and certain inflammatory markers." (PMID 39337936, 2024). "Therefore, this systematic review and meta-analysis sought to investigate the influence of psyllium on hemoglobin A1C (HbA1c), fasting blood sugar (FBS), insulin, and Homeostatic Model Assessment of Insulin Resistance (HOMA IR)." (PMID 38844885, 2024). "Insulin resistance (IR) arises from inadequate physiological responses due to reduced sensitivity of peripheral tissues to insulin, leading to elevated insulin levels through compensatory mechanisms involving pancreatic β-cell insulin production." (PMID 38632455, 2024). "Steroids induce peripheral insulin resistance and inhibit the pancreatic insulin production." (PMID 38352660, 2024). "When insulin resistance is present, the body may produce more insulin to compensate, leading to higher triglyceride levels and impaired glucose regulation." (PMID 39713218, 2024). "While C16:0 and C18:0 ceramides are considered central to the development of obesity, insulin resistance, and metabolic diseases, there is insufficient evidence to support negative regulatory effects of very-long-chain ceramides on insulin sensitivity and metabolic outcomes." (PMID 39606465, 2024).
Insulin resistance (continued). "We propose that metabolic sequelae of trauma such as insulin resistance, hyperglycemia, glucose intolerance, and high plasma insulin levels could be due to inflammatory processes in WAT." (PMID 38653969, 2024). "Furthermore, insulin resistance (IR) commonly occurs in insulin-sensitive tissues such as the liver, adipose tissue, and muscle due to various mechanisms, including endoplasmic reticulum (ER) stress, impaired mitochondrial dynamics, and autophagy dysfunction." (PMID 38247843, 2024). "Importantly, antioxidants have the potential to improve insulin sensitivity, a crucial factor in obesity-related insulin resistance." (PMID 38391792, 2024). "Similar to mtDNA copy number determination, first, the differences between control adipocytes with induced insulin resistance (IR+) and insulin-sensitive (IR−) adipocytes cultured with the appropriate solvent were evaluated to detect any differences in mtDNA-encoded gene expression." (PMID 39339765, 2024). "When an individual with insulin resistance eats they produce abnormally high insulin levels." (PMID 39123463, 2024). "Collectively, insulin resistance in AD underscores the intricate interplay between metabolic dysregulation and neurodegeneration, highlighting the potential therapeutic relevance of targeting insulin signaling pathways for AD prevention and treatment." (PMID 38892488, 2024). "Diabetic patients often experience insulin resistance (reduced sensitivity of cells to insulin), leading to abnormal insulin signal transduction, including reduced expression and function of insulin receptor substrate-1 (IRS-1) and blocked PI3K/Akt signaling pathway." (PMID 39045049, 2024). "Type 2 DM (T2DM) is distinguished by insulin resistance, which might be accompanied by a substantially diminished capacity for insulin secretion." (PMID 39055492, 2024). "High expression of SREBF1 may be a key for postpartum insulin supplementation to improve insulin resistance, significantly reduce NEFA concentrations, and prevent or treat ketosis and fatty liver in obese cows." (PMID 39881718, 2024). "The research suggests that SHBG plays a crucial role in insulin sensitivity, and its decrease may indicate the occurrence of insulin resistance." (PMID 38779450, 2024). "Also, the results demonstrated consistent associations between the VDR-BsmI polymorphism and HOMA-IR, insulin-to-glucose ratio and FIRI insulin resistance index." (PMID 38233797, 2024). "Therefore, their treatment is crucial for hampering or reducing difficulties caused by an endocrine system imbalance such as insufficient insulin secretion or response and insulin resistance in obesity or NAFLD." (PMID 38504163, 2024). "Additionally, an 8-week aerobic exercise intervention increased insulin sensitivity in individuals classified as overweight or sedentary obese with insulin resistance." (PMID 38818523, 2024). "T2D does not cause a decrease in insulin concentration but rather a decrease of its efficiency following insulin resistance." (PMID 38586183, 2024). "This scenario, known as the ‘insulin hypersecretion’ hypothesis, suggests that hyperinsulinemia is an important initiating event in the development of insulin resistance/type 2 diabetes." (PMID 38791525, 2024). "In overweight or obese individuals, body cells generally utilize insulin less efficiently, which may lead to insulin resistance." (PMID 39121323, 2024). "It was suggested that a higher level of isoleucine in serum could reduce the level of circulating insulin and thus be a prophylactic against insulin resistance." (PMID 39795949, 2024). "For the RLR mixture (100 mg/kg Bwt; RA: Lut: RS = 5:1:4), in vivo experiments have shown the potential to relieve insulin resistance by suppressing starch digestion, stimulating metabolism (glucose uptake, absorption, and utilization), and activating insulin sensitivity." (PMID 38903985, 2024).
Insulin resistance (continued). "Increased HBP activity leads to the production of uridine diphosphate N-acetylglucosamine (UDP-GlcNAc), elevated UDP-GlcNAc levels contribute to insulin resistance as a result of the modification of insulin signaling proteins through O-GlcNAcylation, disrupting normal insulin signaling." (PMID 38999025, 2024). "GD disrupts insulin signaling pathways, leading to impaired glucose uptake and insulin resistance." (PMID 39519193, 2024). "Individuals with high visceral adiposity may suffer from increased plasma-free fatty acids due to impaired insulin function related to peripheral Insulin resistance." (PMID 38489287, 2024). "Furthermore, lower lipogenesis in WAT decreases the synthesis of insulin-sensitizing fatty acids and consequently insulin resistance." (PMID 38672494, 2024). "Added sugar foods and high glycaemic rich carbohydrate are rapidly absorbed after consumption leading to an increase in blood glucose and insulin responses, which if sustained over time can lead to glucose intolerance and insulin resistance, corner stones for T2D." (PMID 39462384, 2024). "Hypoglycemia may be present to a much greater degree than usual and insulin resistance may lead to atypically large insulin doses." (PMID 38570742, 2024). "Insulin resistance reduces the binding of insulin to osteoblasts, and OC secretion is insufficient." (PMID 39100278, 2024). "Insulin resistance (IR) is a pathological condition associated with obesity characterized by a reduced responsiveness of insulin-sensitive tissues -such as visceral adipose tissue (VAT), liver, and skeletal muscles-to the effects of insulin." (PMID 38380252, 2024). "Indeed, there is a negative correlation between the serum concentration of omentin-1 and the following: body mass index, insulin resistance index, leptin, plasma glucose, fasting insulin, TNFα, and IL-6." (PMID 38397886, 2024). "But the level of correlation in the insulin-resistant group is mildly smaller than that in the control group, suggesting that insulin resistance might potentially impact aging." (PMID 39123463, 2024). "Limiting the search to titles containing the phrase "insulin resistance or insulin sensitivity" may have led to the oversight of related publications utilizing these concepts as keywords, similar to previous research." (PMID 38195616, 2024). "Insulin resistance and insulin sensitivity were calculated using the HOMA-IR and QUICKI equation." (PMID 38413933, 2024). "In this study, the administration using AS IV could effectively decrease the glucose level in the blood, reduce the level of insulin, and inhibit glucose intolerance and insulin resistance in GDM model rats." (PMID 39885928, 2024). "After 9 weeks of nanophytosomes administration (100 mg chrysin equivalent/kg) to db/db mice, the study demonstrated a decrease in serum glucose, insulin levels and homeostatic model assessment for insulin resistance (HOMA-IR), similar to 200 mg/kg metformin treatment." (PMID 38673748, 2024). "Insulin resistance (IR) is a condition in which cells are insensible to insulin." (PMID 39797110, 2024). "In the longitudinal analysis, all three BCAAs were associated with an increase in fasting insulin and glucose concentrations over time, but not with changes in insulin resistance (as measured by ΔHOMA-IR) or HbA1c." (PMID 39125441, 2024). "Possible proposed mechanisms from in vitro and in vivo studies suggest that mTOR-Is may decrease β-cell mass through apoptosis, impair glucose-dependent insulin secretion, and increase glucose intolerance and insulin resistance." (PMID 38337487, 2024). "Insulin resistance is a hallmark of T2DM, primarily characterized by impaired insulin signaling." (PMID 39684919, 2024). "However, in certain cases hyperglycemia has also been observed, where malaria induced stress hormones and pro-inflammatory cytokines can lead to lower insulin production or insulin resistance." (PMID 39492784, 2024).